TNF (tumor necrosis factor)
Diseases named in the same sentence as TNF in open-access papers (continued):
Sharing a sentence is not in itself a finding about the gene and the disease.
atherosclerosis (continued). "Further, NO inhibits the TNF-α-stimulated expression ofICAM-1 and adhesion of monocytes to endothelial cells and prevent the developmentof atherosclerosis." (PMID 39077008, 2023). "Interleukins (ILs), chemokines, interferon-γ (IFN-γ), and tumor necrosis factor (TNF)-α, are the cytokines commonly associated with atherosclerosis." (PMID 37629526, 2023). "The adipose tissue-derived exosomes induce RAW264.7 macrophages to switch to the M1 phenotype, increase the secretion of pro-inflammatory cytokines (TNF-α, IL-6), and exacerbate atherosclerosis in hyperlipidemic ApoE−/− mice." (PMID 36683743, 2023). "TNF-α-activated signaling contributes to vascular dysfunction, development and progression of atherosclerosis." (PMID 37495992, 2023). "IL-6 and TNF-α are the most attributable pro-inflammatory cytokines that enhance atherosclerosis and metabolic dysregulation in obesity." (PMID 37833312, 2023). "In particular, these terms were mainly related to immunity and inflammation (i.e., IL-17 signalling, cytokine-cytokine interactions, TNF signalling, and lipids and atherosclerosis) and calcium signalling." (PMID 37755981, 2023). "TNF-α is a potent immunomodulator and proinflammatory cytokine that plays a role in many pathological processes such as atherosclerosis." (PMID 37873057, 2023). "Key pathways included cancer pathways, RAGE signaling pathway, lipid metabolism, atherosclerosis, TNF signaling pathway, PI3K-Akt signaling pathway, and apoptotic pathways." (PMID 38001230, 2023). "Pro-inflammatory cytokines, such as IL-6, IL-1β, MCP-1 and TNF-α, are involved in the pathogenesis of atherosclerosis through inducing inflammatory cascades in the heart." (PMID 38041095, 2023). "Atherosclerosis is one of the leading causes of AMI, and inflammatory mediators such as IL-6, TNFα, and CRP are potential biomarkers for the diagnosis of AMI in patients with angina." (PMID 36672669, 2023). "In atherosclerosis, bone marrow mesenchymal stem cells increased production of cytokines, such as TNF-α, IL-6, and IL-1, which regulated the differentiation of HSCs via affecting the hematopoietic microenvironment of bone marrow." (PMID 37525137, 2023). "It has also been reported that TNF-α is one of the inflammatory markers that can promote atherosclerosis." (PMID 36768722, 2023). "The results of KEGG analysis showed that Lipid and atherosclerosis, Cytokine-cytokine receptor interaction, Cholesterol metabolism, TNF signaling pathway, and PPAR signaling pathway are the core regulatory pathways after the elimination of unrelated findings." (PMID 38115108, 2023). "Results from this study suggest that inhibition of TNF-α signaling is a possible mechanism for the prevention of endothelial dysfunction and atherosclerosis progression by these drugs." (PMID 37495992, 2023). "TLR7 can inhibit inflammation in atherosclerosis by secreting TNF-α and IL-10, so it is regarded as a prognosis marker in severe atherosclerosis patients." (PMID 38524701, 2023). "TMAO is also associated with disease processes in murine models of atherosclerosis, where it is tied to foam cell formation, NLRP3 inflammasome activation, and generation of the proinflammatory cytokines IL-1β, TNF-α, and IL-6." (PMID 37720032, 2023). "Lectin-like receptor for oxidized LDL (LOX-1), located on the membrane of ECs, can recognize oxLDL, TNFα, and other stimuli, and plays an important role in the progression of atherosclerosis." (PMID 37833942, 2023). "Mast cells also contribute to atherosclerosis by secretion of cytokines and chemokines such as IL-6, IL-8, TNF-α, IFN-γ, histamine, and proteases." (PMID 37600028, 2023). "For patients with RA, biological DMARDs (tumor necrosis factor inhibitors, IL‐1 inhibitors, IL‐6 receptor inhibitors, and CD20 blockers) are used to manage atherosclerotic CVD risk and prevent atherosclerosis from forming." (PMID 37667491, 2023).
atherosclerosis (continued). "The early 90s focused on traditional mechanisms such as tumor necrosis factor and the mechanism of a nuclear transcription factor in atherosclerosis." (PMID 36873405, 2023). "The most important role in the development of atherosclerosis is TNF-α, TNF-related apoptosis-inducing ligand (TRAIL), TNF-like weak-inducer of apoptosis (TWEAK), CD40L, and their cognate receptors." (PMID 37047399, 2023). "TNF-α, IL-1β and interferon-γ stimulate SMase activity in the endothelial cells of vessels affected by atherosclerosis, thereby increasing the concentration of ceramides in cells, which probably occurs in adipocytes of AT of the heart and coronary arteries." (PMID 37298446, 2023). "Stress hyperglycemia triggers the production of inflammatory factors such as IL-6, IL-8, and TNF-alpha in the body, which can exacerbate atherosclerosis through various intracellular pathways." (PMID 37046267, 2023). "Some of them, such as TNF-α and C-reactive protein, are known to be mediators of atherosclerosis and endothelial alterations by damaging vascular functionality and reducing the nitric oxide (NO) availability." (PMID 38001946, 2023). "Through acute-phase proteins such as CRP or cytokines such as TNF-α and IL-6, chronic inflammation greatly contributes to atherosclerosis in both the tunica intima and tunica media layers of the arterial wall." (PMID 37893519, 2023). "Using KEGG analysis, it was discovered that above genes were mainly concentrated in IL-17, TNF, and lipid and atherosclerosis pathways." (PMID 38115057, 2023). "Topiramate was involved in the IL-17 pathway, endocrine resistance, TNF signaling and lipid and atherosclerosis." (PMID 38137423, 2023). "A previous study linked TUG1 with inflammation as TUG1 knockdown decreased IL-6 and TNF in an animal model of atherosclerosis as well as upregulated inflammatory factor expression by sponging miR-133a in ox-LDL-treated macrophages." (PMID 37736902, 2023). "In fact, the roles of TNF-α and IL-6 in VSMCs have been the subject of extensive research due to their significant implications for cardiovascular diseases such as atherosclerosis, restenosis, and hypertension." (PMID 37873791, 2023). "It is also enriched in multiple pathways, including the IL-17 signaling pathway, the TNF signaling pathway, chemical carcinogenesis receptor activation, Hepatitis B Cellular senescence, Fluid shear stress, and atherosclerosis signaling pathways." (PMID 37680619, 2023). "The serum IL-1β, IL-6, and TNF-α levels were significantly reduced, whereas IL-10 was greatly increased in mice with early and advanced atherosclerosis after GLSP treatment." (PMID 36923537, 2023). "Abnormal immune system response promotes inflammation and inflammatory cytokines (TNFα, IL-6, and IL-1β) that also contribute to the initiation and progression of atherosclerosis and also to the depletion of T cells." (PMID 37627941, 2023). "The effect of TNF-α inhibitors, such as infliximab, etanercept, and adalimumab, in atherosclerosis has been evaluated in preclinical studies or in patients with rheumatological diseases where they have shown anti-inflammatory properties." (PMID 37629526, 2023). "Further, the circulating level of resistin is positively associated with inflammatory biomarkers such as TNF-α, IL-1β, and IL-6, and diseases such as DM2 and atherosclerosis." (PMID 36788619, 2023). "The TNF-alpha inflammation pathway is an important driver of atherosclerosis and formation of vascular plaque." (PMID 37534280, 2023). "The enriched pathways were mainly associated with cancer, the AGE-RAGE signaling pathway in diabetic complications, lipid and atherosclerosis, TNF signaling pathway, PI3K-Akt signaling pathway, and apoptosis." (PMID 38001230, 2023). "Chronic low-grade inflammation also contributes significantly to the pathogenesis of atherosclerosis, due to the effects of tumor necrosis factor-alpha (TNF-α) and interleukin-10 (IL-10)." (PMID 37628963, 2023).
atherosclerosis (continued). "TNFα and IL-1β are classic proinflammatory cytokines and common inducers of EndMT, playing inflammatory roles during atherosclerosis development." (PMID 38268851, 2023). "In the top 30 enriched pathways identified by KEGG analysis, pathways involved included cancer pathway, AGE-RAGE signaling pathway in diabetic complications, lipid and atherosclerosis, TNF signaling pathway, PI3K-Akt pathway, and apoptosis." (PMID 38001230, 2023). "Caspase-3 was enriched in AGE-RAGE signaling, atherosclerosis, cancer, TNF signaling, IL-17 signaling, MAPK signaling, apoptosis and natural killer cell mediated cytotoxicity." (PMID 38196993, 2023). "In cardiovascular diseases, IL-6 and TNF are involved in the pathogenesis of atherosclerosis, myocardial infarction, and heart failure." (PMID 37047011, 2023). "TNF‐α is responsible for the activation of macrophages, Th1 lymphocytes, and endothelial cells in atherosclerosis." (PMID 37822049, 2023). "Acting as a stimulus for M1 macrophages, CHI3L1′s ability to suppress TNF-α secretion is thought to mediate macrophage differentiation and contribute to atherosclerosis." (PMID 38003338, 2023). "It is suggested that MMP-9 and TNF-α levels have regulatory effects on ongoing inflammation, lipid metabolism and atherosclerosis." (PMID 38357561, 2023). "KEGG enrichment analysis demonstrated these apoptosis related DEGs were mainly enriched in cytokine-cytokine receptor interaction, TNF signaling pathway, pathways in cancer, lipid and atherosclerosis, and apoptosis." (PMID 37217794, 2023). "Pro-inflammatory cytokines and chemokines (e.g., MCP-1 and TNF-α) play a key role in the initiation and progression of atherosclerosis." (PMID 36835270, 2023). "Polymorphisms in inflammatory cytokine genes, like interleukin-6 (IL-6) and tumor necrosis factor-alpha (TNF-α), modulate inflammatory responses, promoting atherosclerosis progression." (PMID 37868550, 2023). "TNF-α was considered a proinflammatory cytokine, resulting in an inflammatory disorder during multiple steps of atherosclerosis." (PMID 35774377, 2022). "Pro-inflammatory cytokines such as tumor necrosis factor-α (TNF-α) have a significant role in endothelial dysfunction and atherosclerosis development." (PMID 36294897, 2022). "Significantly, we found that, in a state resembling low-grade inflammation (such as established atherosclerosis), E2 further increased the TNF-α-induced MMP-2 activation in HAECs, with the greatest effect at the lowest concentration." (PMID 36142876, 2022). "Four signaling pathways, namely IL-17 signaling pathway, lipid and atherosclerosis, TNF signaling pathway, and TLR signaling pathway, were selected from the KEGG enrichment results." (PMID 35839049, 2022). "Taken together, our findings reveal that the administration of capsanthin alleviates inflammatory markers in TNF-α-stimulated cultured ECs, and prevents the progression of atherosclerosis in WD-fed ApoE−/−mice." (PMID 35892680, 2022). "TNF-α promotes atherosclerosis by facilitating platelet aggregation and enhancing LDL transport in endothelial cells." (PMID 36501095, 2022). "NF-kappa B promotes the expression of proinflammatory cytokines (such as IL-1, IL-6, and TNF-α) and various atherosclerosis-related genes (including VCAM-1, tissue factor, VEGF, and RAGE)." (PMID 35845584, 2022). "TNF is a tumor necrosis factor that can also promote atherosclerosis by increasing the endocytosis of LDL in endothelial cells, thereby promoting the deposition of LDL in the vascular walls." (PMID 36212940, 2022). "In this way, these genes would further regulate fluid shear stress and atherosclerosis signaling pathway, leishmaniosis signaling pathway, IL-17 signaling pathway, TNF signaling pathway, and many others." (PMID 36624863, 2022).
atherosclerosis (continued). "The KEGG signaling pathway analysis results showed that the up-regulated genes in the S group were mainly enriched in the apoptosis, IL-17 signaling pathway, fluid sheer stress atherosclerosis, and TNF signaling pathway." (PMID 36064702, 2022). "The pro-inflammatory cytokines TNF-α and IL-6 play crucial roles in inflammation and exacerbate atherosclerosis in murine species." (PMID 35625895, 2022). "Adipokines from adipose tissue, such as resistin, leptin, adiponectin, and TNF, play a vital role in the inflammation process, which is the main reason for the development of atherosclerosis." (PMID 36299943, 2022). "PPI network and GO/KEGG pathway enrichment analysis showed that AO toxic compounds mainly targeted PPARG and TNF and regulated the lipid and atherosclerosis signaling pathway." (PMID 36457705, 2022). "KEGG pathway analyses revealed that pathways were remarkably sponged, which involved IL-17 signal path, RA, TNF signal path, and lipid and atherosclerosis." (PMID 35733917, 2022). "This resulted in the upregulation of ICAM-1 on endothelial cells through the activation of TNF-α/NF-κB signalling pathways, which promotes the adhesion of monocytes to ECs, a key event in the initiation of atherosclerosis." (PMID 35736920, 2022). "These can be explained as follows: (i) atherogenic risk factors, like LDL-C and high glucose, and cytokines involved in atherosclerosis, like tumor necrosis factor-alpha (TNF-α) and interferon-γ (IFN-γ), can upregulate AIM2 expression." (PMID 35646157, 2022). "Since endothelial inflammation is a crucial step in atherogenesis, natural products that inhibit TNF-α-induced NF-κB activation and the consequent inflammation are the promising future therapies for atherosclerosis." (PMID 36294897, 2022). "Treatment with TNF-α inhibitors improved endothelial function and ameliorated atherosclerosis in patients with early RA, suggesting that TNFα is a key mediator of premature atherosclerosis in RA." (PMID 36249997, 2022). "Tumor necrosis factor -α (TNF-α) is mainly produced by monocytes and macrophages, and plays an important role in the formation of atherosclerosis." (PMID 35282820, 2022). "Systemic inflammation in IBD patients leads to oxidative stress and elevated levels of inflammatory cytokines such as TNF-α, leading to phenotypic changes in smooth muscle cells that culminate in atherosclerosis and CVD." (PMID 35892915, 2022). "Among the secreted proteins, IL-6, IL1-α and β, IL8, IFNγ, Vascular endothelial growth factor (VEGF), ROS and TNFα are involved in endothelial dysfunction or atherosclerosis." (PMID 35055149, 2022). "The result indicated that 25 genes were mainly enriched in PI3K/Akt signalling pathway, endocrine resistance, TNF signalling pathway, lipid and atherosclerosis, Rap1 signalling pathway, MAPK signalling pathway, etc.." (PMID 36124995, 2022). "Circulating proinflammatory cytokines such as IL-1β and TNF-α are involved in the process of atherosclerosis." (PMID 35215505, 2022). "The pro-inflammatory cytokines TNF-α and IL-1β are known to contribute to the development of atherosclerosis and foam cell formation, further evidencing the detrimental role of PCSK9 in this pathology." (PMID 36012389, 2022). "Previous study showed that selective EGFR deletion in myeloid cells limited their ability to produce IL-6, TNF-α, and to uptake lipids, thereby reducing the development of atherosclerosis." (PMID 35783840, 2022). "Exosomes derived from mature DCs affect endothelial inflammation and atherosclerosis through the membrane tumor necrosis factor-α (TNF-α)-mediated nuclear factor (NF)-κB signaling pathway." (PMID 35055187, 2022). "Tilianin derived from TFDM ameliorates atherosclerosis by inhibiting the production of the NF-κB-dependent proinflammatory cytokines TNF-α and IL-1β via the inhibition of IκB kinase activity." (PMID 35955548, 2022).
atherosclerosis (continued). "Pro-inflammatory cytokines IL-1β, IL-6, and TNFα, released into systemic circulation during active RA, are considered to be the main contributors to atherosclerosis due to their impact on lipid and lipoprotein metabolism, and the biology of the artery wall." (PMID 36297390, 2022). "The progression of atherosclerosis correlates directly with a local increase in TNF-α production in atherosclerotic plaques and blood." (PMID 35350534, 2022). "TNF-α level was elevated in the plasma of patients with acute coronary syndrome, while deletion of TNF-α gene reduced the formation of atherosclerosis in mice." (PMID 36294897, 2022). "IL-17 appears to play a less important role in atherosclerotic plaque development compared to Th1 cytokines (TNF-α and IL-12), and IL-17 confers both proatherogenic and protective effects in atherosclerosis, thus having controversial roles." (PMID 36012327, 2022). "TNF-α promotes the initiation of inflammation by activating T cells and macrophages and can lead to the development of atherosclerosis and glucose metabolic disorders." (PMID 35250385, 2022). "The 31 ferroptosis-related DEGs in endometrial hyperplasia identified 14 days after ligation were mainly enriched in response to oxidative stress, ferroptosis, tumor necrosis factor signaling pathway, and lipid and atherosclerosis." (PMID 36110200, 2022). "Acting on the vascular endothelium, TNFα thus emerges as a key driver for the progression of atherosclerosis." (PMID 36233252, 2022). "Pro-inflammatory mediators such as tumor necrosis factor-alpha (TNF-α) have evidently been shown to induce endothelial activation, which is a key early event implicated in chronic inflammatory diseases such as atherosclerosis." (PMID 35251216, 2022). "The expression levels of hs-CRP, TNF-α, NO and EDN1, PTGIS, and AGT genes at risk of atherosclerosis were significantly decreased." (PMID 36180828, 2022). "TNF-α is a pro-inflammatory cytokine that plays an important role in adaptive immunity and promoting atherosclerosis." (PMID 36703734, 2022). "Early atherosclerosis closely connects with endothelial dysfunction; low-density lipoprotein (LDL), tumor necrosis factor-alpha (TNF-α), and monocytes are some risk factors for facilitating this form of atherosclerosis." (PMID 35208450, 2022). "A previous study reported the link between the gene deletion of EGFR and the reduction in IL-6 and TNFα in myeloid cells, which attenuates atherosclerosis." (PMID 35877429, 2022). "TNF-α is a multifunctional proinflammatory cytokine, which is known to be involved in the pathogenesis of atherosclerosis." (PMID 36013196, 2022). "The top five pathways affected by AG were pathways involved in cancer (hsa05200), TNF signaling pathway (hsa04668), fluid shear stress, atherosclerosis (hsa05418), colorectal cancer (hsa05210), and non-alcoholic fatty liver disease (NAFLD) (hsa04923)." (PMID 35543243, 2022). "The experiment involved incubating human endothelial cells with adropin and TNFα and assessing the expression of the adhesion molecules that are involved in atherosclerosis." (PMID 35955453, 2022). "The results showed that overlapping targets were mainly enriched in lipid and atherosclerosis pathways, pathways in cancer and chemical carcinogenesis-receptor activation, and the TNF signaling pathway." (PMID 36172180, 2022). "The synergistic effect of IFN-γ and TNF-α can promote the formation of atherosclerosis; IL-17 combined with TNF-α or IFN-γ leads to atherosclerosis by accelerating the apoptosis of VSMC." (PMID 35211020, 2022). "In summary, APN improves endothelial dysfunction via the AMPK/NF-κB/TNF-α axis and other signaling pathways, ultimately influencing atherosclerosis development." (PMID 36555264, 2022).